SRC (SRC proto-oncogene, non-receptor tyrosine kinase)
Diseases named in the same sentence as SRC in open-access papers (continued):
Sharing a sentence is not in itself a finding about the gene and the disease.
Stroke (10 papers, 2017 to 2025). Sudden impairment of blood flow to a part of the brain due to occlusion or rupture of an artery to the brain. "Through network pharmacology and computational simulations, key targets associated with musk volatile compounds and stroke, including SRC, EGFR, ESR1, PTGS2, and DRD2, were identified." (PMID 40137146, 2025). "In addition, network pharmacological analyses identified 180 potential targets of the major volatile compounds of musk associated with stroke, and five key targets (SRC, EGFR, ESR1, PTGS2, and DRD2)." (PMID 40137146, 2025). "Studies have shown that SRC regulates smooth muscle contraction after stroke, which leads to increased cerebrovascular tension and poststroke reperfusion injury." (PMID 40137146, 2025). "In summarizing this study, we affirm that our risk assessment model, based on PADGs, specifically APP, THBS1, F13A1, SRC, PPBP, and VCL, presents robust diagnostic capabilities for stroke patients." (PMID 38268925, 2023). "SRC, a non-receptor protein tyrosine kinase encoded by SRC proto-oncogene, exhibits rapid activation within hours following stroke onset, with expression levels progressively increasing in infarcted regions for up to 24 h." (PMID 40948644, 2025). "Symmetrically, SRC is seen to execute a neuroprotective role in stroke." (PMID 38268925, 2023). "Thus, SRC plays a crucial part in cardiovascular and cerebrovascular diseases such as hypertension and stroke." (PMID 32714405, 2020). "Therefore, SRC, EGFR, ESR1, PTGS2, and DRD2 are closely related to the occurrence and development of stroke, and the volatile compounds of musk may treat nerve damage caused by stroke by binding to these key target proteins." (PMID 40137146, 2025). "Previous studies on TFDM also showed its stroke therapeutic effects mainly involve two aspects: first, activating the VEGF/tyrosine protein kinase SRC signaling pathway to promote angiogenesis; second, activating the PI3K/AKT signaling pathway to prevent cell apoptosis." (PMID 41245636, 2025).
Thrombocytopenia (10 papers, 2017 to 2026). A reduction in the number of circulating thrombocytes. "SRC inhibitors have been associated with various adverse events, including bleeding, infection, anemia, thrombocytopenia, diarrhea, edema, pleural effusion, and pulmonary hypertension." (PMID 39661665, 2024). "A recent publication including nine patients with a gain-of-function mutation in the SRC gene demonstrated clinical phenotypes with signs such as thrombocytopenia, myelofibrosis, bleeding, and bone pathology." (PMID 35572556, 2022). "SRC GOF mutation (SRC E527K) has been identified in families with thrombocytopenia progressing into MF and displaying elevated TPO levels." (PMID 28955303, 2017).
asthma (9 papers, 2022 to 2026). "Lonicerin alleviates asthma by exerting anti-inflammatory and immunomodulatory effects through inhibition of the SRC/EGFR pathway." (PMID 41599256, 2026). "Using Gromacs-2022.04, we simulated the molecular dynamics (MD) of a 100 ns protein-ligand complex for EGFR, ALB, MAPK8, ESR1, and SRC, respectively, which are typical core targets for allergic rhinitis and asthma." (PMID 37781715, 2023). "Allergic inflammation in murine asthma model is reported to be regulated by SRC transactivation of EGFR, followed by activation of ERK1/2/NFκB32." (PMID 36163190, 2022). "In our study, we employed a network pharmacology approach to prioritize seven predicted targets (AKT1, VEGFA, EGFR, SRC, MAPK3, MMP9, MAPK1) of baicalein for asthma treatment, and confirmed its high binding affinity to these targets through molecular docking." (PMID 38178132, 2024). "Finally, we obtained 7 predicted targets of baicalein for asthma treatment, namely AKT1, VEGFA, EGFR, SRC, MAPK3, MMP9, MAPK1." (PMID 38178132, 2024). "The top 10 highest degree of targets were EGFR, JAK1/2, MAPK14, VEGF, SRC, mTOR, PI3K, and GSK3B, which might be the critical targets of HHAE for the treatment of asthma." (PMID 36408342, 2022). "Besides transgelin-2, some targets (i.g., ESR1, EGFR, CASP3, and SRC) may be important for the anti-asthmatic effect of glycyrrhizin, and some signaling pathways (i.g., SRC/EGFR signaling pathway) are also promising research directions for improving asthma." (PMID 37711178, 2023).
Hypertension (9 papers, 2014 to 2025). The presence of chronic increased pressure in the systemic arterial system. "Network pharmacology identified ten key bioactive compounds (e.g., liquiritigenin, isoliquiritigenin, and caffeic acid), 149 hypertension-related targets, and ten core targets such as SRC, PIK3CA, PIK3CB, EGFR, and IGF1R." (PMID 41155608, 2025). "Cytochrome P-4501B1 (CYP1B1) induces reactive oxygen species (ROS) to cause inflammation, cardiovascular hypertrophy and hypertension-related endothelial dysfunction, which is mediated by the activation of ERK1/2 and c-SRC signalling pathways." (PMID 34040073, 2021). "In our study, SRC, an SFK family member, was identified as a key target of ZXD in hypertension treatment, showing strong interactions with the core component liquiritigenin." (PMID 41155608, 2025). "Ibrutinib-specific off-targets LCK, JAK3, and FLT3 were predicted to trigger inflammation processes related to hypertension; ERBB2, BLK, SRC, and CSK were predicted to trigger oxidative stress and endothelial dysfunction; and CSK were predicted to trigger the RAAS overactivation." (PMID 40744952, 2025). "Most EGFR, SRC (including dasatinib), RAF (such as BRAF inhibitor HG-6-64-01), and MEK inhibitors displayed antiviral effects, while the majority of hormones, steroid hormones, immunomodulators and various drugs used to treat hypertension or heart conditions showed distinct antifibrotic scores." (PMID 34045585, 2021).
renal carcinoma (9 papers, 2017 to 2025). A carcinoma arising from the epithelium of the renal parenchyma or the renal pelvis. "SRC has been reported to be overexpressed in renal cancer cell lines owing to downregulation of miR-205, which targets and degrades SRC mRNA." (PMID 37439249, 2023). "Src kinase signaling members were also predominant in the core, including SRC, LCK, LYN, FYN and PTPN6, among which LYN has been causally implicated in renal cancer." (PMID 29861861, 2018). "The increase in SRC protein in renal cancer is related to the poor survival prognosis of patients." (PMID 33622324, 2021). "The combination of SRC and PI3K (by saracatinib and GDC-0941, respectively) has been shown to be effective in renal cancer in several pre-clinical models, including PDX models." (PMID 40568132, 2025).
thyroid cancer (9 papers, 2014 to 2025). "With regards to invasion and migration, it has been demonstrated that proNGF induced migration in thyroid cancer cells, through p75NTR/TrkA/sortilin leading to SRC signaling pathway activation." (PMID 30190671, 2018). "Other studies have shown elevated proto-oncogene tyrosine kinase (SRC) activity in invasive thyroid cancer cells; so, we explore bosutinib, a specific inhibitor for SRC, to explore SRC as a mediator of SDH-PTEN crosstalk in this context." (PMID 25149476, 2015). "Our data demonstrate that the combined treatment of BRAF mutated thyroid cancer cells with the BRAFV600E-inhibitor PLX4720 and the SRC-inhibitor dasatinib results in a synergistic increase in the anti-proliferative and apoptotic responses in vitro." (PMID 24994118, 2014). "Here we report that the SRC-inhibitor dasatinib further sensitizes BRAFV600E-positive thyroid cancer cells to the BRAFV600E-inhibitor PLX4720." (PMID 24994118, 2014). "In an effort to enhance the efficacy of BRAFV600E-inhibition in thyroid cancer, we chose to target additional signaling pathways, chiefly SRC signaling." (PMID 24994118, 2014). "SRC is the central mediator of the growth and metastasis of thyroid cancer." (PMID 34840968, 2021). "Dasatinib inhibits the growth and metastasis of thyroid cancer cells by inhibiting the SRC gene." (PMID 34840968, 2021). "In this study, therefore, we sought to address our hypothesis that CS/CSL-associated germline variants in SDHD could alter PTEN nuclear localization through SRC-induced PTEN oxidation in thyroid cancer cells." (PMID 25149476, 2015). "Our observations here suggest that SRC inhibition could be potentially considered for tailoring treatment, at least for thyroid cancers, in the subset of CS/CSL patients carrying germline SDH variants in the context of wild-type PTEN." (PMID 25149476, 2015). "Our observations here may offer a valuable clue exploring potential reasons of drug resistance to SRC inhibitors in some thyroid cancer patients." (PMID 25149476, 2015). "In addition, aberrant somatic activation of SRC is frequent in human cancers including thyroid cancers." (PMID 25149476, 2015). "SRC, on the other hand, was significantly upregulated in BRCA, squamous cell lung cancer (LUSC) and thyroid cancer (THCA), whereas BECN1 was significantly downregulated in KIRC." (PMID 39859167, 2025). "SRC signaling, as evidenced by phosphorylation at tyrosine 416 (pSRC(Y416)), is active in a panel of human and murine PTC and ATC thyroid cancer cell lines harboring BRAFV600E." (PMID 24994118, 2014). "Additionally, PF-573228, another FAK inhibitor, interacts with SRC by impeding the formation of the SRC/FAK complex and integrin activation through the inhibition of FAK, resulting in reduced cell proliferation in thyroid cancer." (PMID 35205315, 2022). "We show that SRC inhibition could rescue SDHD dysfunction-induced cellular phenotype and tumorigenesis only when wild-type PTEN is expressed, in thyroid cancer lines." (PMID 25149476, 2015). "Inhibition of either oncogenic BRAF or SRC has marked anti-tumor effects in mouse models of thyroid cancer, however, neither drug induces notable apoptosis." (PMID 24994118, 2014). "To further identify the effect of our SRC kinase inhibitor on thyroid cancer cell lines, we examined the activation of HIF-1α by ROS with or without SRC inhibition." (PMID 25149476, 2015).
depression (8 papers, 2022 to 2025). "Topological analysis of the bioactive-target-pathway network indicated that MAPK1, PIK3R1, EGFR, AKT1, and SRC were the core targets enriched in crucial signaling pathways associated with treating depression by A. laxiflora." (PMID 38505421, 2024). "In summary, these results suggest that MG‐derived VDBP mainly targets the megalin receptor of inhibitory neurons, thereby initiating the downstream SRC pathway and leading to neuronal synaptic damage, ultimately participating in the development of depression." (PMID 39716879, 2025). "Here, we report for the first time that MG‐derived VDBP acts on neuronal megalin and the SRC signaling pathway to mediate neuron and synaptic damage, leading to depression‐like behaviors in mice." (PMID 39716879, 2025). "We demonstrated that MG‐derived VDBP interacts with the neuronal receptor megalin to activate the downstream SRC signaling pathway and induce apoptosis, leading to depression." (PMID 39716879, 2025). "Molecular docking analysis results exhibited that core targets of depression, such as SRC, EGFR, PIK3R1, AKT1, and MAPK1, bind stably with the analyzed bioactive compounds of A. laxiflora." (PMID 38505421, 2024). "Therefore, the administration of the SRC inhibitor led to depression-like behavior in hormone-stimulated pregnancy mice." (PMID 39936089, 2025). "Among the top 10 hub gene targets, MAPK1, AKT1, PIK3R1, EGFR, STAT3, and SRC were the most enriched targets in the selected KEGG pathway, suggesting their critical role in the pathogenesis of depression." (PMID 38505421, 2024). "SRC, a non-receptor tyrosine kinase of SRC family kinase (SFK), is abundant at synaptic sites to demonstrate an important role in depressive disorder." (PMID 39936089, 2025).
colitis (7 papers, 2018 to 2025). Inflammation of the colon. "JAM-A phosphorylation at tyrosine residue Y280 has been reported as a cytokine-induced and SRC-mediated mechanism for barrier function inactivation in human and animal models of colitis." (PMID 34226680, 2021). "In addition, enhanced COX-2 and SRC activity was observed in DSS-treated mice, which contributed to colitis pathogenesis." (PMID 38034999, 2023). "Importantly, a prior work utilizing Lgr5-Cre-driven GPBAR1 conditional knockout mice revealed that intestinal stem cells exhibited impaired self-renewal, reduced differentiation capacity, and delayed post-colitis regeneration, accompanied by disrupted YAP/SRC signaling pathway activation." (PMID 41228488, 2025).
colon adenocarcinoma (7 papers, 2015 to 2024). "In colon adenocarcinoma, P1 isoform expression that is normally present in the superficial differentiated epithelium is lost and instead exhibits a cytoplasmic shift due to SRC-mediated phosphorylation and degradation of HNF4α25." (PMID 37974020, 2023).
endometrial cancer (7 papers, 2015 to 2024). Primary or metastatic malignant neoplasm involving the endometrium (mucous membrane that lines the endometrial cavity). "Current research mainly focuses on the role of SRC in the initiation and progression of endometrial cancer; however, the specific mechanisms of its involvement in chemoresistance have not yet been systematically elucidated." (PMID 39664567, 2024). "Pathogenic somatic SRC variants disturbing the SH2–Y530 interaction result in continuous SRC activation as found in colon and endometrial cancer." (PMID 33255186, 2020). "In this way, the signaling-SRC-Rho GTPase axis is activated in endometrial cancer cells, changing cell motility and proliferation." (PMID 32443784, 2020). "Consequently, the NMU signaling SRC-Rho GTPase cascade is an excellent target for preventing endometrial cancer development in obese phenotype." (PMID 32443784, 2020). "In our studies in NMU-depleted endometrial cancer cells, we observed that not only was there a decrease in the levels of adhesion signaling-related molecules, but there was also an impairment of downstream c-SRC activity." (PMID 26849234, 2016). "Furthermore, the specific mechanisms of the involvement of SRC in resistance to chemotherapy and targeted therapy in endometrial cancer, such as EMT and lipid metabolism, remain unclear." (PMID 39664567, 2024). "In addition to its role in chemoresistance, the specific regulatory mechanisms of SRC in ferroptosis in the context of endometrial cancer remain unknown, particularly under conditions of iron homeostasis imbalance in the tumor microenvironment." (PMID 39664567, 2024). "Thus, it is concluded that NMU pathway positively controls the adhesion signaling-SRC-Rho GTPase axis in the tested endometrial cancer cells and that changes in cell motility and proliferation can occur when there is manipulation of NMU signaling in these cells either in vitro or in vivo." (PMID 26849234, 2016). "Conversely, EMP2 was identified as an early predictor of endometrial cancers with unfavorable outcome by activation of protein tyrosine kinase 2 (PTK2 or FAK) and v-src avian sarcoma viral oncogene homolog (SRC)." (PMID 25940704, 2015). "Therefore, we can not exclude the possibility that the impairment of SRC activity can contribute directly, or has a synergistic effect with the decrease of CD44 co-receptor level, to dampen the EGF-induced or TGFβ1-induced mesenchymal marker expression in the NMU-knockdown endometrial cancer cells." (PMID 26849234, 2016).
endothelial dysfunction (7 papers, 2014 to 2025). In vascular diseases, endothelial dysfunction is a systemic pathological state of the endothelium (the inner lining of blood vessels) and can be broadly defined as an imbalance between vasodilating and vasoconstricting substances produced by (or acting on) the endothelium.
laryngeal carcinoma (7 papers, 2017 to 2025). Carcinoma that arises from the laryngeal epithelium. "Multivariate Cox analysis further revealed active SRC expression as an independent predictor of cancer-specific mortality in patients with laryngeal carcinomas." (PMID 31731442, 2019). "Active SRC expression specifically emerged as an independent predictor of poor prognosis in patients with laryngeal cancer." (PMID 31731442, 2019). "Moreover, active SRC expression now emerges as an independent predictor of cancer-specific mortality in laryngeal cancer." (PMID 31731442, 2019).
medulloblastoma (7 papers, 2014 to 2026). A malignant, invasive embryonal neoplasm arising from the cerebellum. "ERBB4 is a tyrosine kinase receptor and is critical during cerebellum and medulloblastoma development, while SRC signaling controls important biological/oncogenic processes, including proliferation, apoptosis, cell adhesion and motility." (PMID 35011618, 2021).
nasopharyngeal carcinoma (7 papers, 2016 to 2023). A carcinoma arising from the nasopharyngeal epithelium. "Increased p-SRC (Tyr419) levels have also been detected in nasopharyngeal carcinomas, both in tissue samples and in plasma, and correlated with tumor aggressiveness, distant metastasis, and unfavorable prognosis." (PMID 31731442, 2019).